RDX (radixin)
Diseases named in the same sentence as RDX in open-access papers (continued):
Sharing a sentence is not in itself a finding about the gene and the disease.
hearing loss (8 papers, 2011 to 2025). "Beyond the morphological changes caused by the absence of CLIC5, its deficiency has been shown to disrupt the localization of proteins such as RDX, TPRN, and PTPRQ, which are linked to hearing loss." (PMID 40859056, 2025). "Homozygous missense variants in RDX (OMIM 179410), CABP2 (OMIM 607314), and ESRRB (OMIM 602167) were found to contribute to hearing loss in three individuals." (PMID 32681043, 2020). "Identification of the c.1076_1079delTTAA (p.Ile359Lysfs*6) deletion gives a better understanding of the role the RDX gene plays in hearing impairment." (PMID 22567349, 2011). "Therefore, understanding the physiopathology of genes such as RDX and increasing our awareness of its contribution to this burden of delayed diagnosis could improve the care of children with hearing impairment." (PMID 33361775, 2020). "The mechanism we present here, where GRXCR2 restricts taperin from entering the stereocilia shaft, may also explain the morphological defects and hearing loss caused by mutations of CLIC5, radixin, PTPRQ, MYO6, Fam65b, or other components located at the basal region of stereocilia." (PMID 30380417, 2018).
pancreatic cancer (8 papers, 2014 to 2024). "Overall, the proteomic studies revealed the association of radixin, moesin, c14orf166, S100P and hemopexin in LN metastasis in pancreatic cancer." (PMID 39195316, 2024). "For instance, overexpression Moesin and Radixin are present in pancreatic cancers with lymph node metastases as compared with those where metastases are absent." (PMID 27746764, 2016). "Whereas both moesin and radixin were found upregulated in lymph node metastases of pancreatic cancer, the level of ezrin expression was unaffected, but its phosphorylation status did change." (PMID 26983550, 2016). "Interestingly, radixin is reported to possibly act as a scaffold protein responsible for cell surface localization of PD-L1 in a pancreatic cancer cell line." (PMID 37371811, 2023). "In CAPG-overexpressing pancreatic cancer cells, phosphorylation status of other actin-modulating proteins (cofilin, ezrin/radixin) was not significantly altered, suggesting possible involvement of other cellular proteins, such as ornithine aminotransferase and enolase." (PMID 31360146, 2019).
melanoma (6 papers, 2012 to 2023). A malignant, usually aggressive tumor composed of atypical, neoplastic melanocytes. "MCAM-mediated activation of PI4K signalling was reported to help recruitment of actin-linking ezrin–radixin–moesin to cell protrusions and promote melanoma cell motility." (PMID 36291660, 2022). "They discovered several novel melanoma exosomal proteins, such as p120 catenin, radixin, and immunoglobulin superfamily member 8 (PGRL)." (PMID 23056502, 2012). "On the other hand CYT-low metastatic melanomas had recurrent amplifications in loci 5p15.33 (TERT), 6p25.1 (CDYL), 7p22.2 (RAC1), 12q15 (MDM1) and recurrent deletions in 5q31.2 (CTNNA1, FGF1), 11q22.3 (FDX1, RDX, ZC3H12C), and 15q14 (RASGRP1, CSNK1A1P1, SPRED1)." (PMID 33779796, 2021).
glioblastoma (5 papers, 2015 to 2024). The most malignant astrocytic tumor (WHO grade IV). "High expression of radixin in glioblastoma U251 cells, prostatic hyperplasia, and neoplasia were observed." (PMID 39457653, 2024). "Similar to another study in glioblastoma, miR-31 was shown to suppress the migration and invasion of glioma cells by directly targeting the cytoskeletal protein, radixin." (PMID 26260454, 2015). "The suppression of radixin upregulates thrombospondin-1 (TSP-1) and E-cadherin and downregulates matrix metalloproteinase (MMP) -9 in glioblastoma U251 cells, which may be associated with cell migration and invasion." (PMID 39457653, 2024). "No radixin mRNA expression was detected in OC clinical samples, a human glioblastoma cell line, LN18 (generous gift of Professor Lazarovici, HUJI) was used as positive control." (PMID 27622508, 2016). "One member of the ERM family of proteins, moesin, was reported overexpressed in glioblastoma (GBM), but two other ERM proteins, ezrin and radixin, show no significant differential expression, and knockdown of moesin alone reduced the migration of GBM cells." (PMID 29416017, 2018).
lung carcinoma (5 papers, 2011 to 2022). "MSN is a member of the ezrin–radixin–moesin family of proteins involved in various aspects of cell migration, adhesion, and invasion, and DPYSL3 and heat-shock chaperonin (HSP60) were linked to lung cancer metastasis." (PMID 35512017, 2022). "However, moesin expression patterns can vary by cancer type, as moesin, like radixin, has been shown to be down regulated in cases of lung cancer." (PMID 21235778, 2011). "This may be true, as previous work has shown radixin to be down regulated in some instances of lungs cancer in comparison to non-tumor lung tissue." (PMID 21235778, 2011).
colon adenocarcinoma (4 papers, 2021 to 2024). "Radixin, moesin, and ezrin were preferentially distributed on the plasma membrane in human colon adenocarcinoma cells, However, the mRNA levels of ezrin and moesin were observed to be higher than those of radixin." (PMID 39457653, 2024). "Moreover, the gene correlation analysis revealed a positive correlation of PD-L1 with ezrin and moesin but not radixin in the clinical human colon adenocarcinoma samples from the TGCA database." (PMID 34577564, 2021).
deafness (4 papers, 2012 to 2022). An inherited or acquired condition characterized by the complete loss of the ability to hear from one or both ears. "There are a few reports of RDX variants associated with deafness in existing research." (PMID 31250571, 2019). "RDX, protein tyrosine phosphatase receptor Q (PTPRQ), and TPRN which are associated with deafness, were mislocalized in fused stereocilia of CLIC5A-deficient mice." (PMID 36035115, 2022). "In addition to GRXCR2 and taperin, several proteins linked to deafness are concentrated at or near the stereocilia base, including Fam65b, PTPRQ, CLIC5, radixin, and PDZD7." (PMID 30380417, 2018). "Radixin and the ERM-interacting protein CLIC5 are expressed in hair cell stereocilia and loss of these proteins causes deafness, suggesting that an ELMO-ERM interaction may mediate actin cytoskeleton organization in hair cell stereocilia." (PMID 22558334, 2012).
glioma (4 papers, 2014 to 2023). A benign or malignant brain and spinal cord tumor that arises from glial cells (astrocytes, oligodendrocytes, ependymal cells). "ERM (Ezrin, Radixin, and Moesin) proteins play an important role in cancer migration and invasion and interact with NKCC1 protein in glioma migration." (PMID 24555568, 2014).
cervical cancer (3 papers, 2021 to 2025). A primary or metastatic malignant neoplasm involving the cervix. "Specifically, increased expression of the radixin protein can promote the progression of cervical cancer." (PMID 40098697, 2025). "In conclusion, the interactions within the HIF1A-AS2-miR-34b-5p-RDX axis are crucial for cervical cancer progression, highlighting HIF1A-AS2 and miR-34b-5p as promising biomarkers for cancer diagnosis and prognosis." (PMID 40098697, 2025). "Additionally, HIF1A-AS2 serves as a molecular sponge for miR-34b-5p, regulating radixin expression, which contributes to the advancement of malignant traits in cervical cancer cells." (PMID 40098697, 2025). "In another human cervical cancer cell line, OMC4, all three ERM were detected at protein levels, but the relative expression levels of radixin and moesin were lower than that of ezrin." (PMID 34577118, 2021). "QRT-PCR was used to detect the expression of HIF1A-AS2 and radixin in 20 cervical cancer patient tissues and their matched normal tissue samples." (PMID 40098697, 2025).
Cognitive impairment (3 papers, 2024). Abnormal cognition is characterized by deficits in thinking, reasoning, or remembering. "However, despite the downward trend in ROCK expression and a decrease in energy metabolism, data on how the Rho‐GTPase‐ROCK pathway participates in Radixin phosphorylation and mediates cognitive impairment caused by sevoflurane is still insufficient." (PMID 38698533, 2024). "Studies have demonstrated that increased Radixin phosphorylation leads to the clustering of α5GABAARs at extrasynaptic sites, contributing to cognitive impairment in mice." (PMID 39491498, 2024). "Additionally, intervention in the RhoA/ROCK2 signaling pathway via pharmacological approaches and genetic modification attenuates the phosphorylation of radixin, thereby mitigating cognitive impairments induced by sevoflurane." (PMID 38825816, 2024). "It is hypothesized that fasudil inhibits the ROCK II/Radixin pathway activated by sevoflurane and surgical trauma, preventing Radixin phosphorylation and the accumulation of α5GABAARs on the cell membrane, thus ameliorating cognitive deficits in postoperative mice." (PMID 39491498, 2024).
lung adenocarcinoma (3 papers, 2011 to 2020). A carcinoma that arises from the lung and is characterized by the presence of malignant glandular epithelial cells. "RDX and moesin are downregulated in some lung adenocarcinomas, suggesting that these two molecules function as tumor suppressors in the early oncogenic stages." (PMID 33065998, 2020). "Despite this, it, like radixin, has been shown to be down regulated in select cases of lung adenocarcinoma." (PMID 21235778, 2011). "Radixin is an ~80 kDa protein that has been shown to be down regulated in some cases of lung adenocarcinoma." (PMID 21235778, 2011).
pancreatic ductal adenocarcinoma (3 papers, 2022). An infiltrating adenocarcinoma that arises from the epithelial cells of the pancreas. "We also found that as a dominant ERM protein, radixin acts as a principal scaffold protein for PD-L1 in KP-2 human pancreatic ductal adenocarcinoma cells." (PMID 35807113, 2022). "We also demonstrated that as a predominant ERM protein, radixin primarily regulates the cell surface localization of PD-L1 in human pancreatic ductal adenocarcinoma cells (KP-2)." (PMID 35456317, 2022). "We also reported that radixin is involved in the plasma membrane expression of PD–L1 as a predominant ERM protein in KP–2 human pancreatic ductal adenocarcinoma cells." (PMID 35566582, 2022).
tongue squamous cell carcinoma (3 papers, 2020 to 2021). A squamous cell carcinoma that arises from the tongue. "Further, miR-409-3p expression is also decreased in tongue squamous cell carcinoma, and suppresses the proliferation, invasion, and migration of the tongue squamous cell carcinoma cells by targeting RDX." (PMID 32391354, 2020). "For instance, miR-409-3p may delay the proliferation of tongue squamous cell carcinoma cells by inhibiting of radixin (RDX) to decrease its migratory and invasive abilities, which may be a potential target for the clinical treatment of tongue squamous cell carcinoma." (PMID 34338153, 2021).
hepatocellular carcinoma (2 papers, 2014 to 2020). A malignant tumor that arises from hepatocytes. "A recent report showing that HCV infection reduces the expression of ERM proteins moesin and radixin provides an explanation for our observation that HCV infection limits CD81-dependent hepatoma spread." (PMID 24662676, 2014). "We simultaneously demonstrated that increased expression of ARHGEF10L stimulates hepatocellular tumorigenesis by activating the RhoA-ROCK1 (Rho-associated coiled-coil kinase-1)-phospho-ERM (phospho-Ezrin/Radixin/Moesin pathway) and EMT (epithelial-mesenchymal transition) in hepatocellular carcinoma." (PMID 32565805, 2020).
Hyperbilirubinemia (2 papers, 2010 to 2019). An increased amount of bilirubin in the blood. "Similarly, radixin is the dominant ERM protein expressed in the liver, and radixin-deficient mice exhibit liver defects leading to hyperbilirubinemia." (PMID 20806059, 2010). "In radixin knockout mice the two main phenotypes are hearing impairment and hyperbilirubinemia, although this defective liver phenotype has not been observed in human patients with mutations in radixin." (PMID 31018575, 2019).
inflammatory bowel disease (2 papers, 2015 to 2025). A spectrum of small and large bowel inflammatory diseases of unknown etiology. "Consistent with that, another group showed upregulation of the Abi2 gene together with the genes for the fibroblast growth factor, profilin-2, and radixin during tumorigenesis of inflammatory bowel disease- (IBD-) associated CRC." (PMID 26345720, 2015).
lupus (2 papers, 2023 to 2024). "The RhoA/ROCK pathway has been implicated in lupus pathology in a prior study that showed that increased phosphorylation of the ezrin, radixin, moesin (ERM) proteins interact with CD44 to promote the adhesion, migration and inflammatory response of T lymphocytes." (PMID 37790522, 2023).
metastatic disease (2 papers, 2007 to 2020). "Interestingly, FoxM1 is consistently upregulated in metastases, while RDX was upregulated in only two of the four patients with metastatic disease, confirming the heterogeneity of metastatic prostate cancer." (PMID 17430594, 2007). "However, although not statistically significant, RDX was more frequently mutated in patients with metastatic disease, in agreement with its possible role as a pro-metastatic gene." (PMID 33065998, 2020).
ovarian carcinoma (2 papers, 2022 to 2024). A malignant neoplasm originating from the surface ovarian epithelium. "In contrast, there are no reports describing the expression of radixin in human ovarian cancers, except in human ovarian granulosa cells." (PMID 35566582, 2022). "The treatment of ovarian cancer cells with LPA also promotes O-GlcNAcylation of ezrin–radixin–moesin (ERM) cytoskeletal proteins, and although the exact mechanism is not entirely understood, LPA-induced activation of ERM suggests the role of LPA in the adhesion and migration of ovarian cancer cells." (PMID 38607068, 2024).
thyroid cancer (2 papers, 2019 to 2022). "Incubating NTHY cells with EVs isolated from thyroid cancer cell lines did not affect the Alix, Moesin and Radixin expression (data not shown)." (PMID 35328683, 2022).
cervical squamous cancer (1 paper, 2022). "Although the relative mRNA expression level of PD-L1 was low in HCS-2 cell, those of ezrin, radixin, and moesin in HCS-2 cells rank high among human uterine cervical squamous cancer cell lines analyzed." (PMID 35807113, 2022).
cholestasis (1 paper, 2023). Impairment of the bile flow caused by obstruction within the liver, or outside the liver in the bile duct system. "In cholestasis, Radixin dephosphorylation promotes MRP2 translocation and structural membrane remodeling." (PMID 37928027, 2023). "To check for Ezrin-mediated effects on the canalicular membrane constitution in cholestasis, we stained liver tissue obtained from Ezrko/ko and B6 mice after surgery for Mrp2 and Radixin as well as pERM and Radixin." (PMID 37928027, 2023). "In cholestatic diseases, changes in Radixin, but not Ezrin, activation are associated with canalicular remodeling, one of the major driving forces of cholestasis." (PMID 37928027, 2023). "Two opposing functions have been described, with activated Radixin stabilizing MRP2 at the canalicular membrane of hepatocytes, whereas activated Ezrin removes MRP2 from the membrane, promoting cholestasis." (PMID 37928027, 2023). "Homeostasis of the canalicular pole in hepatocytes is maintained exclusively by Radixin but not Ezrin, and Radixin dysfunction promotes cholestasis." (PMID 37928027, 2023). "We demonstrated the absence of Ezrin in hepatocytes during health and cholestasis, leaving Radixin not only as the predominant but only ERM protein expressed in hepatocytes and emphasizing its importance in organization and maintenance of the canalicular membrane structure and function." (PMID 37928027, 2023).
clear cell renal cell carcinoma (1 paper, 2022). "RDX knockdown increased the intracellular SN-38 concentration, indicating enhanced anti-tumor activity, in human clear cell renal cell carcinoma Caki-1 cells." (PMID 36499305, 2022).
colorectal adenocarcinoma (1 paper, 2021). The most common type of colorectal carcinoma. "We initially assessed the gene expression levels of PD-L1, ezrin, radixin, and moesin in LS180 cells and Caco-2 cells which is also a representative human colorectal adenocarcinoma cell line and was used for comparison with LS180 cells." (PMID 34577564, 2021).
cyst (1 paper, 2015). A sac-like closed membranous structure that may be empty or contain fluid or amorphous material. "Importantly, fortifying the link between the apical membrane and actin cortex by overexpression of the ezrin/radixin/moesin ortholog ERM-1, significantly rescued cyst formation and ruptures in the pigv-1(qm34) mutant." (PMID 25807459, 2015).
diabetes (1 paper, 2024). "We recently found significantly altered radixin in Schwann cells during elevated glucose, suggesting that it may be related to diabetes-induced nerve injury." (PMID 39457653, 2024).
dilated cardiomyopathy (1 paper, 2020). Cardiomyopathy which is characterized by dilation and contractile dysfunction of the left and right ventricles. "Staining of the ERM protein radixin indicated quite dramatic modifications in the structure of the area of IDs in patients with dilated cardiomyopathy and in cardiomyocyte cultures." (PMID 32774516, 2020).
endometriosis (1 paper, 2025). The growth of functional endometrial tissue in anatomic sites outside the uterine body. "The roles of RDX and MSN in endometriosis are even less well understood." (PMID 40072086, 2025).
epilepsy (1 paper, 2011). A brain disorder characterized by episodes of abnormally increased neuronal discharge resulting in transient episodes of sensory or motor neurological dysfunction, or psychic dysfunction. "The potency of RDX at the GABAA convulsant site (Ki of 21.1 μM) is similar to pentylenetetrazol, a convulsant commonly used in animal models of seizure and epilepsy that is also known to bind at the picrotoxin convulsant site." (PMID 21362589, 2011).
glaucoma (1 paper, 2009). Increased pressure in the eyeball due to obstruction of the outflow of aqueous humor. "The objective of this study was to investigate association of several genes that have not been subject to an association study with glaucoma cases so far but might be functionally linked to glaucoma pathogenesis (RDX, SNX16, MFN1, MFN2, PARL, SOD2)." (PMID 19754948, 2009).
influenza (1 paper, 2017). An acute viral infection of the respiratory tract, occurring in isolated cases, in epidemics, or in pandemics; it is caused by serologically different strains of viruses (influenzaviruses) designated A, B, and C, has a 3-day incubation period, and usually lasts for 3 to 10 days. "Our previous study also provided evidence for the involvement of Rho/ROCK and PKC pathways in influenza-induced hyperpermeability in microvascular cells via phosphorylating Ezrin/Radixin/Moesin (ERM)." (PMID 29059211, 2017).
liver cancer (1 paper, 2015). An epithelial or non-epithelial malignant neoplasm that arises from the liver. "MiR-31 is well known metastatic suppressor by direct targeting integrin family, RhoA and RDX in various cancers but unknown in liver cancer." (PMID 25797269, 2015).
myocarditis (1 paper, 2019). Myocarditis is a condition that is characterized by inflammation of the heart muscle (myocardium). "In addition, we demonstrate that the induction of acute myocarditis involves the engagement of CD43 cytoplasmic tripeptide sequence KRR to ezrin-radixin-moiesin cytoskeletal proteins." (PMID 31197200, 2019).
normal tension glaucoma (1 paper, 2009). "Results suggested that genetic variation in five of the candidate genes (RDX, SNX16, OPA1, SOD2 and CYP1B1) is unlikely to confer major risk to develop normal tension glaucoma in the German population." (PMID 19754948, 2009).
oral cancer (1 paper, 2020). "In oral cancer cells, SNAIL was previously associated with changes in RHO activity and phosphorylation of EZRIN-RADIXIN-MOESIN family, but no precise mechanism was described." (PMID 32664538, 2020).